Y_RNA (Y RNA )
Gene: Miscellaneous RNA gene on chromosome 8 (100,755,099 to 100,755,195, reverse strand). Ensembl gene ENSG00000202001.
Homologues: Orthologues: chimpanzee Y_RNA (100% identical), macaque Y_RNA (85% identical). Paralogues in human: Y_RNA (88% identical), RNY3 (87% identical), Y_RNA (87% identical), Y_RNA (86% identical), Y_RNA (85% identical), RNY3P1 (84% identical), Y_RNA (84% identical), RNY3P16 (82% identical), Y_RNA (82% identical), RNY3P14 (81% identical), RNY3P4 (81% identical), Y_RNA (81% identical), and 95 more.